PSMB2 (proteasome 20S subunit beta 2)
Diseases named in the same sentence as PSMB2 in open-access papers (continued):
Sharing a sentence is not in itself a finding about the gene and the disease.
cancer (14 papers, 2008 to 2025). A tumor composed of atypical neoplastic, often pleomorphic cells that invade other tissues. "Over-expressions of PSMB1/2/4/7/8/9/10 mRNA were found in ccRCC tissues compared to normal tissues, transcriptional levels of PSMB2/3/4/6/8/9/10 were significantly positively associated with patients' individual cancer stages and grades." (PMID 35693739, 2022). "Related studies have also confirmed that PSMB2 affected the cancer cells proliferation and invasion." (PMID 38467767, 2024). "The study identified genes in the ubiquitin proteasome system, including proteasome subunit alpha 1 (PSMA1) and proteasome subunit beta 2 (PSMB2), as essential genes in cancer cells." (PMID 35740614, 2022). "In our study, significantly higher mRNA expression of PSMB2 was found in ccRCC tissues compared to normal tissues, and was positively related with patients' individual cancer stages and tumor grades." (PMID 35693739, 2022). "All six HUB nodes correlated with at least one cancer type, and FYN and PSMB2 correlated with poor OS in patients with five different cancers." (PMID 32933107, 2020). "Except for PSMB2, the relationship between these hub genes and cancer has been reported by previous studies." (PMID 28191039, 2017). "Previous studies have indicated that PSMB2 expression in para-cancer tissues is lower than that in tumor tissues, which may be the reason that PSMB2 induces the malignant degree of tumors and various subtle and complex pathways." (PMID 38467767, 2024). "In addition to MCM2 to MCM7, six downstream oncogenic targets of c-MYC implicated in cancer survival and metabolism including PSMA1, PSMA6, PSMB2, HDAC2, LDHA and SPRING were positively correlated with IFITM3 in 71 GC specimens using the Cho dataset." (PMID 35941699, 2022). "PSMB2 is part of the proteasome complex, which is typically upregulated in many cancers." (PMID 36362114, 2022). "However, other anti-cancer strategies such as the attack to protein degradation function by blocking PSMB2 proteasome component has been also uncovered by the presented methodology." (PMID 20015360, 2009). "Finally, results from our study showed that higher mRNA expressions of PSMB1/2/4/7/8/9/10 were found in ccRCC tissues compared to normal tissues, transcriptional levels of PSMB2/3/4/6/8/9/10 were significantly positively related with patients' individual cancer stages and grades." (PMID 35693739, 2022). "The PSMB2-5 and PSMB9 expression was also increased in Ki-67-positive tumors, which is consistent with increase of these genes’ expression in malignant tumors compared to normal tissue." (PMID 39796785, 2025). "Of the 102 driver genes present in at least four networks, we found that PSMA, PSMB, and PSMD were the cancer driver genes with a crucial role in the proteasome pathway (with also RPN1/2, PSMA3/5/6/7, PSMB2/3/4/8/9, PSMD2/3/4/7/11/12/14)." (PMID 29304754, 2018). "Moreover, based on our data, PSMB2 and RPL32 represent promising candidate reference genes for other lung pathologies such as COPD and cancer." (PMID 18671841, 2008).
tumor (9 papers, 2012 to 2025). "By incorporating PSMB2 expression and several factors, including WHO, IDH status, 1p/19q codeletion, sex and age, into an OS histogram, we found that PSMB2 overexpression was associated with worse tumor prognosis." (PMID 38467767, 2024). "Previous studies have shown that PSMB2 affects tumor invasion, proliferation, the cell cycle and sensitivity to chemotherapy drugs by regulating the tumor microenvironment." (PMID 38467767, 2024). "The “limma” package was applied to probe high PSMB2 expression groups and low PSMB2 expression groups to reveal the potential mechanism by which PSMB2 accelerates tumor evolvement." (PMID 38467767, 2024). "Furthermore, ssGSEA also showed that PSMB2 may regulate immune checkpoint expression, which may promote the activity of chemotherapeutic drugs against tumor cells by enhancing PSMB2 expression and decreasing the therapeutic effects." (PMID 38467767, 2024). "Significant ilQTLs, the majority of which of somatic origin, were identified in immune-relevant genes, including B2M, HLA genes, CANX, LDHA, PSMB2, and HNRNPR, which are known to affect the tumor immune landscape." (PMID 38773080, 2024). "NUDT21 inhibited HCC proliferation, metastasis and tumorigenesis, at least in part, by suppressing proteasome subunit beta type-2 (PSMB2) and CXXC-type zinc finger protein 5 (CXXC5), acting as a tumor suppressor in hepatocellular carcinogenesis." (PMID 32346127, 2020). "However, in contrast to normal epithelial tissues, the expression of FBXL5, PSMB2, and PSMD12 was markedly decreased in tumor epithelial cells." (PMID 41444773, 2025). "In our study, we found that high PSMB2 expression may induce the upregulation of CD274, CTLA4, HAVCR2, LAG3, PDCD1, PDCD1LG2 and SIGLEC15, which are molecules on immune cells that facilitate tumor immune escape." (PMID 38467767, 2024).
hematologic diseases (1 paper, 2015). "A particular focus on the PSM family of proteasome subunits identified with our approaches, may be valuable; screening for genetic abnormalities identified PSMB2 has been reported in ovarian carcinogenesis, while PSM gene polymorphisms are risk factors for other hematologic diseases." (PMID 26474455, 2015).
infection (1 paper, 2019). The state of being infected such as from the introduction of a foreign agent such as serum, vaccine, antigenic substance or organism. "Except for PSMB2 and PSMB10, all other PSMBs were upregulated after influenza A virus (IAV, PR8 strain) infection of THP-1 cells." (PMID 30682859, 2019).
neurological diseases (1 paper, 2022). "In addition, small nuclear ribonucleoprotein D3 polypeptide (SNRPD3) and PSMB2 are also related to neurological diseases." (PMID 35559016, 2022).
PSMB2 also shares sentences with these, for which no sentence is quoted: amyotrophic lateral sclerosis (2 papers); ovarian carcinoma (2); Alzheimer disease (1); bacterial infection (1); chronic myelogenous leukemia (1); colorectal cancer (1); diabetes (1); gastric cancer (1); glioblastoma (1); Huntington disease (1); leukemia (1); lung carcinoma (1); lung diseases (1); lymphoblastic leukemia (1); lymphoma (1); oligodendroglioma (1); osteosarcoma (1); Parkinson disease (1); prion disease (1); pulmonary sarcoidosis (1); schizophrenia (1); varicocele (1).